PNMA8B (PNMA family member 8B)
Synonyms: KIAA1183; PNMAL2
Tractability: No criterion of Open Targets' tractability assessment is met for any kind of drug.
Gene: Protein-coding gene on chromosome 19 (46,486,906 to 46,495,879, reverse strand). Ensembl gene ENSG00000204851.
Genetic constraint (gnomAD): Loss-of-function variants: 0 observed, 0.23 expected, observed/expected ratio (o/e) 0, 90% interval 0 to 1.88. That is too few expected variants to judge how well the gene tolerates losing a copy. Missense variants: 773 observed, 736.56 expected, observed/expected ratio (o/e) 1.05, 90% interval 0.99 to 1.11. Synonymous variants: 338 observed, 328.75 expected, observed/expected ratio (o/e) 1.03, 90% interval 0.94 to 1.12.
Homologues: Orthologues: rat Pnma8b (63% identical), mouse Pnma8b (63% identical). Paralogues in human: PNMA8A (17% identical), PNMA6E (13% identical), PNMA6F (12% identical), PNMA1 (12% identical), PNMA3 (11% identical), PNMA2 (11% identical), PNMA6A (11% identical), PNMA5 (11% identical), MOAP1 (11% identical), PNMA8C (8% identical), CCDC8 (6% identical), ZCCHC18 (6% identical), and 1 more.
Diseases named in the same sentence as PNMA8B in open-access papers:
PNMA8B is named in the same sentence as 2 diseases in open-access papers, as found by Europe PMC text mining. Sharing a sentence is not in itself a finding about the gene and the disease. The quoted sentences say what the papers report.
cancer (1 paper, 2021). A tumor composed of atypical neoplastic, often pleomorphic cells that invade other tissues. "Many of the genes such as JHY, PLAAT1, PNMA8B, RPL37P6, SNX32, UGGT2 and Y_RNA have not been related to any cancer, yet." (PMID 33672117, 2021).
PNMA8B also shares sentences with these, for which no sentence is quoted: retinal disease (1 paper).